ARPC3P3 (actin related protein 2/3 complex subunit 3 pseudogene 3)
Gene: Processed pseudogene on chromosome 11 (94,188,449 to 94,188,997, reverse strand). Ensembl gene ENSG00000256745.
Diseases named in the same sentence as ARPC3P3 in open-access papers:
ARPC3P3 is named in the same sentence as 1 disease in open-access papers, as found by Europe PMC text mining. Sharing a sentence is not in itself a finding about the gene and the disease.
ARPC3P3 shares sentences with these, for which no sentence is quoted: lung adenocarcinoma (1 paper).